SH2D1A (SH2 domain containing 1A)
Description:
Cytoplasmic adapter regulating receptors of the signaling lymphocytic activation molecule (SLAM) family such as SLAMF1, CD244, LY9, CD84, SLAMF6 and SLAMF7. In SLAM signaling seems to cooperate with SH2D1B/EAT-2. Initially it has been proposed that association with SLAMF1 prevents SLAMF1 binding to inhibitory effectors including INPP5D/SHIP1 and PTPN11/SHP-2. However, by simultaneous interactions, recruits FYN which subsequently phosphorylates and activates SLAMF1. Positively regulates CD244/2B4- and CD84-mediated natural killer (NK) cell functions. Can also promote CD48-, SLAMF6 -, LY9-, and SLAMF7-mediated NK cell activation. In the context of NK cell-mediated cytotoxicity enhances conjugate formation with target cells (By similarity). May also regulate the activity of the neurotrophin receptors NTRK1, NTRK2 and NTRK3.
Synonyms: DSHP; SAP; XLP; MTCP1; XLPD; EBVS; IMD5; LYP; SAP/SH2D1A; XLPD1
Tractability: PROTAC: ubiquitination databases record sites on it; its protein half-life has been measured.
Gene: Protein-coding gene on chromosome X (124,227,868 to 124,373,197, forward strand). Ensembl gene ENSG00000183918.
Subcellular location: Cytoplasm
Subcellular location (Human Protein Atlas): Cytosol
Pathways (Reactome):
Immune System: Immunoregulatory interactions between a Lymphoid and a non-Lymphoid cell
Gene Ontology:
Molecular function: protein binding; protein-macromolecule adaptor activity
Biological process: natural killer cell activation; negative regulation of T cell receptor signaling pathway; regulation of immune response; cell-cell signaling; cellular defense response; immune system process
Cellular component: cytoplasm; cytosol
Gene-disease validity (ClinGen):
ClinGen rates the evidence that SH2D1A causes each of these diseases.
X-linked lymphoproliferative disease due to SH2D1A deficiency (X-linked): Definitive.
Homologues: Orthologues: chimpanzee SH2D1A (100% identical), pig SH2D1A (95% identical), dog SH2D1A (94% identical), macaque SH2D1A (91% identical), rabbit SH2D1A (89% identical), rat Sh2d1a (89% identical), mouse Sh2d1a (88% identical), guinea pig SH2D1A (77% identical), tropical clawed frog sh2d1a (54% identical), zebrafish sh2d1ab (53% identical), Caenorhabditis elegans unc-26 (18% identical), Drosophila melanogaster CG9784 (16% identical), and 4 more. Paralogues in human: SH2D1B (38% identical), INPP5B (28% identical), INPP5D (28% identical), INPPL1 (27% identical), OCRL (23% identical), SYNJ1 (23% identical), SYNJ2 (20% identical), INPP5E (18% identical), INPP5F (18% identical), INPP5J (18% identical), FIG4 (17% identical), SACM1L (16% identical), and 1 more.